IGF1R (insulin like growth factor 1 receptor)
Diseases named in the same sentence as IGF1R in open-access papers (continued):
Sharing a sentence is not in itself a finding about the gene and the disease.
tumor (continued). "Several reports have shown that sE-cad inhibits apoptosis and has an important function in cancer progression via activation of several signaling cascades linked to tumor progression, such as the EGFR and IGF-1R signaling pathways, and consequent activation of ERK1/2 and PI3K signaling." (PMID 37760996, 2023). "Picropodophyllin (PPP) is a selective IGF-1R inhibitor and is involved in inhibiting tumor growth." (PMID 36635683, 2023). "In addition, PCAT6 enhances IGF1R mRNA stability via the PCAT6/IGF2BP2/IGF1R RNA–protein trimer, thereby upregulating IGF1R expression and promoting PCa bone metastasis and tumor growth." (PMID 38117350, 2023). "The most significant CRISPRi screened enhancer E_349 interacts with MEF2A and LRRC28 instead of its designed target IGF1R, which implies that HRR-associated enhancers could modulate multiple uncharacterized melanoma cancer genes for tumor survival." (PMID 37904237, 2023). "miR-128 induces its tumor-suppressing effect, such as anti-proliferative and anti-metastasis effects, by inhibiting tumor-associated signaling pathways, such as WNT, ERK, EGFR, IGF1R, or BCL2." (PMID 37371047, 2023). "Notably, we found that blocking integrin-mediated cell adhesion diminishes IGF1R and AKT activation in T-ALL cells co-cultured with tumor-associated myeloid cells." (PMID 37805579, 2023). "Furthermore, KIAA1324 has been reported to counteract insulin signaling by interacting with insulin receptor (INSR) and insulin-like growth factor 1 receptor (IGF1R) and inhibit cell proliferation, supporting the tumor-suppressive role of KIAA1324." (PMID 37612293, 2023). "Taken together, these observations support the hypothesis that the role of IGF1R in the primary tumor phenotype is highly context dependent." (PMID 35784559, 2022). "We hypothesize that reduced expression of let-7c-5p contributes to the overexpression of IGF1R in ccRCC cells, which contributes to tumor progression and metastasis." (PMID 36289686, 2022). "Studies have found higher expressions of several components of the IGF system (including IGF-1, IGF-2, and IGF-1R) in normal rectal mucosa compared with colonic mucosa, which probably suggests a more pronounced tumor-promoting effect of the IGF system in rectal cancer." (PMID 35296101, 2022). "Notably, about 50% of BC express the activated form of IGF1‐R, which sustains tumor growth, survival, and motility." (PMID 36056637, 2022). "IGF-1R is known to play a pivotal role in promoting tumor growth 9-12." (PMID 35401828, 2022). "In addition, trastuzumab-induced growth arrest of HER2-positive tumour cells is counteracted by an increase in insulin-like growth factor-1 receptor (IGF-IR) signalling." (PMID 36329884, 2022). "Accordingly, IGF1R signaling was reported to protect tumor cells from apoptosis." (PMID 35688943, 2022). "While loss of IGF1R is sufficient to drive a partial EMT phenotype and collective invasion to promote metastasis, alterations in the tumor microenvironment may also be required for increased tumor extravasation." (PMID 36568144, 2022). "In addition, overexpression of miR-99a/b in HCC cells results in significant inhibition of tumor growth by suppressing the expression of IGF1R and MTOR." (PMID 35328346, 2022). "Thus, altering cadherins in DN-Wnt1 primary tumor epithelial cells rescues the compromised adherence suggesting these changes in E- and P-cadherins due to reduced IGF1R are necessary for metastasis." (PMID 36568144, 2022). "Typically, tumor cells, including lung cancer cells, have a high level of IGF-1R expression." (PMID 35203638, 2022). "Since we found high mRNA expression levels of IGF1R in tumor cells, we wanted to understand whether IGF1R/IGF1 axis plays a role in cell migration." (PMID 35574343, 2022).
tumor (continued). "The mechanisms by which IGF1R regulates tumor metastasis could include intrinsic epithelial mesenchymal transition (EMT) changes as well as alterations to the tumor microenvironment (TME) secondary to the genetic changes in the tumor epithelium." (PMID 36568144, 2022). "Moreover, significantly higher expression of tumor IGF-1R was found in patients with type 2 diabetes with some cancers (non-small cell lung cancer and colorectal cancer)." (PMID 35158824, 2022). "IGF-1R confers protection to tumor cells with a malignant phenotype against antitumor therapy." (PMID 36555406, 2022). "Interestingly, INSR signaling has frequently been discussed as a possible compensatory mechanism for tumor cells when IGF1R is inhibited; however, these data suggest a positive correlation between IGF1R expression and INSR expression in human tumors." (PMID 35784559, 2022). "Interestingly, we found a direct correlation between the body weight of the mice and the tumor load, as well as a trend of elevated IGF1R mRNA expression levels correlating with increased tumor load." (PMID 35574343, 2022). "The median of IGF-1R mRNA level was 0.1510for tumor tissues and 0.02900for tumor margins." (PMID 36713521, 2022). "IGF1R plays an important role in tumour cell proliferation and apoptosis." (PMID 36452079, 2022). "They point out, that the IGF1R signaling axis influences tumor development in a progressive manner." (PMID 35574343, 2022). "Notably, tumor epithelium with reduced IGF1R resulted in increased P-cadherin expression in DN-Wnt1 and K8iKOR-Wnt1 bipotential cells." (PMID 36568144, 2022). "Therefore, our findings suggest that tumor growth and disease severity are influenced by IGF1R signaling." (PMID 35574343, 2022). "Hence, the suppression of IGF-1R signaling is considered to be a promising strategy to inhibit tumor growth and improve survival in multiple cancers." (PMID 36233084, 2022). "Therefore, co-targeting PI3K, mTOR, and IGF1R proved to be effective in reducing tumor growth and decreasing cell migration and invasion." (PMID 35760832, 2022). "Moreover, we found a direct correlation between the tumor load and IGF1R mRNA expression levels of total lung cells." (PMID 35574343, 2022). "High IGF-1R expression and elevated IGF-1 circulating levels have been correlated with the increased risk and progression of BC with poor prognosis through promoting cell proliferation, invasion, anti-apoptosis, and tumor angiogenesis." (PMID 35843988, 2022). "Moreover, because the activation of IGFs/IGF-1R signaling results in the bypass pathway, the combination of IGF-1R mAbs/TKIs and other RTKs as anti-tumor agents is considered to a more effective strategy in cancer therapy." (PMID 36233084, 2022). "Furthermore, we found slightly increased EGFR and drastically increased IGF1R expression on tumor cell surface after elevating the glucose concentration in the cell culture medium." (PMID 35574343, 2022). "Accordingly, inactivation of IGF1R was recently reported to delay tumor progression." (PMID 35688943, 2022). "The protein level of IGF-1R decreased in the tumor xenografts with LINC01291 depletion." (PMID 33674778, 2022). "Finally, the signaling crosstalk between insulin and insulin-like growth factor-1 receptor (IGF-1R) is closely related to tumor development." (PMID 35933633, 2022). "More recently, work in the MTB-IGF1R model revealed that expression of the microRNA cluster miR-200b/200a/429 suppresses tumor initiation driven by IGF1R overexpression although the intricacies of the mechanism remain unclear." (PMID 35784559, 2022). "Indeed, mir-378 was reported to modulate the phenotype of RMS cells through IGF1R regulation, whereas miR-206 over-expression reduced tumor growth in vivo by inhibiting c-MET." (PMID 36430468, 2022). "IGF-1/IGF-1R axis contributes to the proliferation and invasion of tumor cells." (PMID 36003786, 2022).
tumor (continued). "Furthermore, the distribution of IGF‐1R inside and outside lipid rafts is closely related to the survival and apoptosis of tumour cells." (PMID 34939255, 2022). "We try to explain the result in this way: The proliferation and development of CAFs are regulated by PI3K/AKT/mTOR signaling pathway, and CAFs might promote tumor progress via IGF1R/AKT1/mTOR pathway in tumor microenvironment." (PMID 35768785, 2022). "Indeed, numerous efforts have been made to develop inhibitors that target IGF-1R signaling, some of which have exhibited a wide range of anti-tumor effects 18-20 and have entered clinical trials 21-23." (PMID 35401828, 2022). "While tumor suppressors might differ in their organ-specific expression, mechanisms of activation, type of tumors involved and other parameters, they share the IGF1R pathway as a common response path." (PMID 36479090, 2022). "A common conclusion of numerous published reports investigating IGF/IGF1R function in mammary tumorigenesis in vivo is that dysregulation of this pathway is sufficient to either induce tumorigenesis or to modulate the primary tumor phenotype (for summary)." (PMID 35784559, 2022). "Here, we show that IGF1R is required to maintain a metastasis suppressive tumor microenvironment." (PMID 36568144, 2022). "IR and IGF-1 receptors (IGF-1R) play important roles in the induction and maintenance of cell proliferation, differentiation and phenotype, and are essential for carcinogenic transformation, tumor growth, and metastases." (PMID 35158824, 2022). "Importantly, however, the mechanistic questions still remain as to how both driving and blocking IGF signaling via IGF1R result in a tumor promoting phenotype." (PMID 35784559, 2022). "However, we found that both PAPPA and IGF1 were predominantly expressed in the stroma of ILC, while IGF1R was expressed within the tumor epithelium." (PMID 35205651, 2022). "IGF-1R was reported as regulating apoptosis and its overexpression in tumor tissues contributing to an antiapoptotic effect by improving cell survival, with its activation resulting in transmitting signals downstream through the PI3K-AKT1-MTOR and MAPK pathways." (PMID 36556276, 2022). "Furthermore, IGF1R deficiency also attenuated TGFβ, an EMT promoter favoring tumor invasion, metastasis, and transdifferentiation of cancer-associated fibroblasts (CAFs)." (PMID 35688943, 2022). "The function of IGF1R and its downstream signaling in tumor cells is still incompletely understood." (PMID 35574343, 2022). "Furthermore, the overexpression in tumors is often modest, and only a relatively low expression level (10,000–30,000 receptors per cell) is necessary for the tumor to respond to IGF-1R-targeting antibodies." (PMID 35890370, 2022). "Thus, either reduced Igf1r expression or reduced IGF1R function in mammary epithelium promotes metastasis of the primary Wnt1 tumor cells." (PMID 36568144, 2022). "Moreover, we noticed a correlation between the tumor load and the weight as well as IGF1R mRNA expression." (PMID 35574343, 2022). "Therefore, a deeper understanding of cancer biology has led to the development of anti-tumor drugs targeting the specific oncogenic substrate IGF-1R." (PMID 36233084, 2022). "It has been reported that IGF1R increases the metastasis in cancer cells by inducing anchorage-independent growth, which became evident from a pre-clinical trial that showed an over-expression of IGF1R in the tumor initiation site as well as in the site where metastasis took place." (PMID 35631368, 2022).
tumor (continued). "Notably, FOXA1 expression in A549 cells reduced the efficacy of the anti-angiogenic drug nintedanib to inhibit xenograft tumor growth, whereas a combination of nintedanib with IGF1R inhibitor linsitinib or mTORC1 inhibitor rapamycin enhanced tumor control." (PMID 35974000, 2022). "Furthermore, adherent DN-Wnt1 tumor epithelial cells had increased vimentin suggesting mostly basal cell adhesion with reduced IGF1R." (PMID 36568144, 2022). "IGF1 and GAS6 can then reciprocally affect tumor cells, via the IGF1R/AXL-AKT axis." (PMID 36612058, 2022). "One question that arises from inhibiting IGF1R in our tumor models is whether there may be compensatory expression or activation of the insulin receptor (INSR)." (PMID 36568144, 2022). "Moreover, miR-99b-5p mimics transfected HBMSCs obviously inhibited tumor progression by downregulating IGF1R in animal model in vivo." (PMID 35030978, 2022). "Downregulation of AFAP1-AS1 by upregulating the IGF1R oncogene via sequestration of miR-133a could suppress the tumor cell growth and invasion in PaC." (PMID 33768092, 2021). "Importantly, scRNAseq identified PGR and IRS-1 enrichment in metastases compared to primary tumours, whereas IGF1R expression trended downward in metastases." (PMID 33144693, 2021). "IGF-1R knockdown via lentivirus-mediated RNAi could remarkably suppress tumor cell growth and apoptosis through attenuating the expression level of midkine in HCC cells." (PMID 33768092, 2021). "IGF1R mediates resistance to cisplatin treatment in different tumor types." (PMID 33673232, 2021). "CD68+/CD163+ TAMs were found to surround IR/IGF1R-stained PDAC tumor cells." (PMID 34638472, 2021). "Silencing of IGF1R exerted effects similar to miR-133a overexpression suggesting that the tumor suppressive function of miR-133a could depend on the regulation of the IGF1R gene." (PMID 34484116, 2021). "The suppression of the insulin-like growth factor-1 receptor (IGF-1R) could be another tumor suppressive mechanism exerted by miR-375 expression." (PMID 34830902, 2021). "Overexpression of HMGA1 and Sp1 drives enhanced expression of the IGF1R and IR in tumor cells." (PMID 34440844, 2021). "The oncogenic signaling network may be influenced by the regulation of IGF1-R by E-cadherin, particularly because E-cadherin itself is involved in mechanisms of escape of tumor cells and metastasization." (PMID 33477996, 2021). "As a result, controlling IGF-1R signaling pathways by antagonizing MUC1 could be a critical step during tumor development." (PMID 33836774, 2021). "While inhibiting both the IGF1R and the IR-A might represent an advantage to avoid compensatory mechanisms in tumor cells, blockade of the IR-B compromises glucose metabolism." (PMID 34440844, 2021). "The influence of βArr1 or βArr2 on the IGF-1R signalling pathway may also indicate their potential inhibitory effect on cell proliferation, invasion, and tumour development in TNBC cells." (PMID 33452359, 2021). "In contrast, IGF-1R expression decreases with cancer dedifferentiation, suggesting that the IGF-2/IR-A loop plays a more important role than does the IGF-1/IGF-1R loop in thyroid cells dedifferentiation, the acquisition of a stem-like phenotype, tumor progression, and metastasis." (PMID 33669363, 2021). "Overexpression of miR-223 by relating IGF-1R could inhibit tumor growth in nude mice and also increase the sensitivity to erlotinib." (PMID 33768092, 2021). "Interestingly, over-expression and over-activation of IGF-1R in cell tumour lines predominantly triggers activation of the RAF/MAPK and PI3K/Akt pathways, which induces proliferation and inhibits apoptosis." (PMID 33739284, 2021). "Furthermore, high expression level of IGF-1 and IGF-1R were closely connected with high degrees of tumor infiltrates, including CD4+ T cell, dendritic cells, and macrophages." (PMID 34804946, 2021).
tumor (continued). "As a consequence, utilizing the off-target IGF1R suppressor ceritinib may pave the way for the remedy of tumor cells driven by IGF1R and IGF2." (PMID 33768092, 2021). "Since blocking IGF1R prevented the rescue phenotype mediated by IGF2 supplementation, we explored whether blocking the IGF1R pathway with AEW541 could enhance the anti-tumor efficacy of isiPI3K in sensitive and resistant cell lines." (PMID 34067117, 2021). "Via employing CRISPRCas9 gene-editing system IRAIN could compete in cis with the overlapping IGF1R promoter, and thereby suppress the IGF1R signaling cascade that in turn attenuate tumor cell proliferation and metastasis in BCa cells." (PMID 33768092, 2021). "Notably, silencing of Trop2 in cancer cells combined with IGF1R inhibitor significantly decreased the proliferation of tumor cells and reshaped the NSCLC TME in vivo and in vitro, including the recruitment of macrophages." (PMID 34335947, 2021). "In addition to the impact of circulating IGF1 on the hazard of developing a tumor, the expression and ligand-dependent activation (phosphorylation) of the IGF1R are regarded as key prerequisites for oncogenic transformation." (PMID 34204736, 2021). "PLEKHS1 expression was significantly increased in G3T1 compared to G1Ta tumours (p = <0.01), whilst IGFBP2, IGFBP4, and IGF1R were significantly reduced in the more advanced tumour group (p = <0.010.03, <0.01, respectively), which were similar results to those observed in CIS." (PMID 34681810, 2021). "In addition, loss-of-heterozygosity of IGF2R favors the interaction between IGF2 and IGF1R in different tumor types." (PMID 33673232, 2021). "The miR‐195‐5p can inhibit IGF‐1R and has a tumor‐suppressive effect." (PMID 34118183, 2021). "Besides, high IGF-1R levels in primary tumor samples have been reported to be predictors of shorter disease-free survival, but data on the prognostic value of the IGF-1R for overall survival are contradictory." (PMID 33829018, 2021). "In numerous cancers, including OS, IGF1R may promote the chemotherapeutic resistance of tumor cells." (PMID 34876132, 2021). "IGF-1R-targeted therapy reveals tumour growth inhibition in TNBC tumour graft MC1." (PMID 34946732, 2021). "Immunoprecipitation studies suggest that the majority, if not all, of the IGF-1R in tumor cells is associated with Sdc1, potentially making SSTNIGF1R a highly specific cancer therapy." (PMID 34778093, 2021). "Since the IGF/IGF-1R signaling pathway is a target of cancer therapies, investigation into the associations between the tumor microenvironment and IGF/IGF-1R signaling may aid in the development of therapeutic strategies." (PMID 33669204, 2021). "IGF-1R knockdown via siRNA could upregulate the expression level of IGFBP-3 in tumor drug resistance cells and lead to promoting the sensitivity of LC cells to cisplatin and radiation." (PMID 33768092, 2021). "Furthermore, the upregulation of tumour suppressor miR-122 by activated FXR suppressed the insulin-like growth factor-1 receptor (IGF-1R) and cyclin G1 resulting in decreased cell proliferation in cancer cells and tumour growth in a mouse model." (PMID 35006466, 2021). "Moreover, we show that blocking IGF2 stimulation activity, using an inhibitor of the IGF1 receptor (IGF1R), enhances isiPI3K efficacy and displays a synergistic anti-tumor effect in vitro and superior anti-tumor activity ex vivo and in vivo." (PMID 34067117, 2021). "The combination of the anti-IGF1R mAb h7C10 and the mTOR inhibitor rapamycin significanlty inhibited in vivo xenograft tumor growth, preventing tumor escape observed after the anti-IGF1R mAb h7C10 treatment alone and limiting the potential problem of mTOR inhibitors-evoked up-regulation of AKT." (PMID 34440844, 2021). "Consistently, IGF1R silencing reduced the ability of tumor cells to form colonies." (PMID 33918477, 2021).